IRF5 (interferon regulatory factor 5)
Diseases named in the same sentence as IRF5 in open-access papers (continued):
Sharing a sentence is not in itself a finding about the gene and the disease.
Insulin resistance (10 papers, 2017 to 2025). Increased resistance towards insulin, that is, diminished effectiveness of insulin in reducing blood glucose levels. "Such early adaptation, underpinned by ATM mitochondrial respiration, is a key event that precedes IRF5 deficiency’s protective metabolic phenotype at the stage of systemic insulin resistance (LT-HFD)." (PMID 36042203, 2022). "Genes with a positive association with inflammation, chemotaxis, insulin resistance, and inflammatory cell death, such as Irf5, Alox5ap, Tlrs, Cd84, Ccr5, Ccl9, and Casp1, were downregulated by EPA." (PMID 32906847, 2020). "These associations support previous studies linking IRF5 to metabolic dysfunction and insulin resistance, and further suggest that in men, IRF5 may play a more direct role in linking immune activation to metabolic impairment." (PMID 40943154, 2025). "In men, IRF5 may serve as a biomarker and potential association with insulin resistance, while in women, it may reflect broader immune activation with less direct metabolic consequence." (PMID 40943154, 2025). "Decreased GHITM expression and loss of cristae organisation occur at an early stage of DIO and represent an IRF5-dependent mechanism that may contribute to loss of microenvironmental homeostasis and development of insulin resistance." (PMID 36042203, 2022). "Together, these data suggest a potential role for IRF5 in glucose metabolism impairment and insulin resistance in men, whereas in women leaning more toward immune signaling than metabolic regulation." (PMID 40943154, 2025). "In this study, we aimed to investigate the sex-related variation in AT IRF5 expression and its relationship with inflammatory markers and insulin resistance in overweight and obese individuals." (PMID 40943154, 2025). "Our own studies have shown that IRF5 is metabolically responsive, and its dysregulated activity plays a role in adipose tissue and liver inflammation upon insulin resistance." (PMID 37978231, 2023). "Further, in this regard, our data show that the increased IRF5 expression also associated positively with HOMA-IR, which is an indicator of the loss of glucose homeostasis and induction of insulin resistance." (PMID 32806763, 2020). "The transcription factor interferon regulatory factor 5 (Irf5) plays an important role in polarizing macrophages towards an inflammatory phenotype and promoting insulin resistance and hepatic fibrosis." (PMID 29107297, 2017). "We were data-driven in resolving the current mechanism, in which we combined public datasets with our own RNA-seq to reveal that a transcriptional target of IRF5 impairs macrophage mitochondrial respiration at the early stage of glucose intolerance but prior to the onset of insulin resistance." (PMID 36042203, 2022). "Notably, IRF5 expression in overweight/obese males, but not females, was significantly associated with metabolic dysfunction, showing positive correlations with fasting blood glucose, HbA1c, insulin, and homeostatic model assessment for insulin resistance (HOMA-IR) levels." (PMID 40943154, 2025).
colitis (9 papers, 2018 to 2025). Inflammation of the colon. "used Helicobacter hepaticus-induced colitis coupled with an anti-IL-10R mAb in Irf5-/- mice and found the frequencies of DC populations during ongoing inflammation remained unchanged compared to steady-state." (PMID 38179052, 2023). "Irf5 knockout hindered CD11c+ mucosal macrophage formation, unveiling IRF5’s contribution to pro-inflammatory CD11c+F4/80+ macrophages during inflammation, driving colitis development." (PMID 38179052, 2023). "The transcription factor interferon regulatory factor 5 (IRF5) aggravates experimental colitis by increasing the CD4 T-cell expression of Th1- and Th17-related cytokines and reducing the expression of Th2-related cytokines." (PMID 36769019, 2023). "The recent single-cell investigation using the Helicobacter hepaticus-induced colitis model, highlights interferon regulatory factor 5 (IRF5)’s role in mucosal macrophage differentiation." (PMID 38179052, 2023). "MiR-146b also targeted IRF5 expression to inhibit the activation of M1 macrophages and ameliorate colitis." (PMID 37909731, 2023). "Similar to colitis mice, miR-144/451 expression was ablated, paralleled with increased IRF5 levels in DCs from IBD." (PMID 35967345, 2022). "We also identified that IRF5 is a direct target gene of miR-144 in facilitating the activation of DCs in colitis." (PMID 35967345, 2022). "Indirectly, IRF5-driven inflammatory mediators may compromise the barrier function, increasing intestinal permeability and perpetuating colitis." (PMID 41007813, 2025). "To investigate whether miR-144/451 abnormality-induced DCs activation is involved in DSS-induced mouse colitis, we first assayed the expression of miR-144/451 and IRF5 in DCs from colitis mice." (PMID 35967345, 2022). "In addition, IRF5 in CD4+ T cells promotes Th1 and Th17 associated cytokines, decreases Th2 associated cytokines and enhances the severity of experimental colitis in mice." (PMID 35967345, 2022). "This is further supported by animal models where a reduction in IRF5 expression attenuated colitis in mice, but also led to impaired clearance of intestinal pathogens, supporting a modeltogether where homeostasis requires a fine balance in the immune system’s response to gut flora." (PMID 36155972, 2022). "Thus, our data indicate that miR-144/451 may repress DCs activation in DSS-induced colitis by targeting IRF5." (PMID 35967345, 2022). "MiR-146b can also target interferon regulatory factor 5 (IRF5) to inhibit the activation of M1 macrophages and improve colitis in vivo." (PMID 37909731, 2023). "miR144 targets 3`UTR of IRF5 to suppressing DCs activation and ameliorating DSS-induced colitis in mice." (PMID 35967345, 2022). "The underlying mechanism of prevention involves modulation of polarization of macrophages via suppression of protein known as interferon regulatory factor 5 (IRF5) and enhanced the expression of IRF4 expression in dextran sodium sulfate-induced colitis in mice." (PMID 35656442, 2022).
COVID-19 (9 papers, 2021 to 2025). A disease caused by infection with severe acute respiratory syndrome coronavirus 2. "Recent investigations report an elevated expression of genes encoding IRF1, IRF5, IRF7, JAK2, and PML in severe COVID-19 patients." (PMID 38022551, 2023). "Viruses can enter platelets, activate endosomal TLRs (TLR7/TLR9) and downstream MYD88-IRAK4-IRAK1-IKKβ (and presumably IRF5), possibly contributing to COVID-19 thrombocytopenia and clotting irregularities." (PMID 33936053, 2021). "Here a case is made for considering IRAK4 or IRF5 inhibitors as potential therapies for the “cytokine storm” of COVID-19." (PMID 33936053, 2021). "Hypoxia leads to an increased dependence on NF-κB and decreased dependence on IRF5, which is what is seen in COVID-19 patients." (PMID 34108245, 2021). "Overactivation of IRF5 can trigger a cytokine storm in COVID-19." (PMID 41516283, 2025). "The increased expression of IRF5 is also related to lymphopenia, and the specific loss of cytotoxic CD8+ lymphocytes and classical monocytes, as seen in patients with type 2 diabetes with severe COVID-19." (PMID 35406000, 2022). "Vice versa, genes down-regulated in CD14+-monocytes during severe COVID-19 were under significant positive influence by PIRAT, headed by the PU.1-suppressed genes IRF5 and ITGAX." (PMID 35998224, 2022). "IRF5 is a transcription factor involved the production of type I IFN and other immune mediators and has been suggested as a therapy-relevant COVID-19 marker." (PMID 35998224, 2022). "This notion was further corroborated in qRT-PCR and FACS validations, which confirmed the control of S100A8, S100A9, ITGAX, and IRF5 by PIRAT and regulation of these factors during COVID-19." (PMID 35998224, 2022). "Thus, IRF5 inhibition protects from hyperinflammation whether induced by viral or bacterial infection, the latter a common complication of acute respiratory distress syndrome, although its incidence in COVID-19 is only just being investigated." (PMID 33936053, 2021). "Increased activity of interferon regulatory factor 5 (IRF5) may aggravate pathology in both AD and COVID-19, or the comorbidity of the two, as a result of blood glucose elevations caused by T2D." (PMID 34833377, 2021). "IRF5 is constitutively expressed by pDCs, especially in females who produce more IFN-α on TLR stimulation than males, making dysregulation of immune responses in COVID-19 in females less likely." (PMID 33936053, 2021). "IRF5 expression in classical monocytes is increased 2.1-fold in patients with and without diabetes admitted to the ICU due to COVID-19." (PMID 35406000, 2022).
glioma (9 papers, 2020 to 2025). A benign or malignant brain and spinal cord tumor that arises from glial cells (astrocytes, oligodendrocytes, ependymal cells). "The nanoparticles delivering mRNAs encoding interferon regulatory factor-5 (IRF-5) and its activating kinase IKKβ were infused into glioma-bearing mice." (PMID 35967394, 2022). "We found that IRF1, IRF2, IRF5, IRF7, IRF8, and IRF9 were upregulated in glioma compared with normal tissue." (PMID 33902005, 2021). "In summary, this study showed that IRF1, IRF2, IRF5, IRF8, and IRF9 mRNA levels were increased in glioma compared to normal tissue." (PMID 33902005, 2021). "We found that IRF1, IRF2, IRF5, IRF8 and IRF9 were significantly upregulated in glioma compared to normal brain tissue." (PMID 33902005, 2021). "Among the 260 grade II, 267 grade III, and 173 grade IV glioma patients, significant correlations were observed between IRF1 (p = 8.00E-61), IRF2 (p = 6.80E-18), IRF3 (p = 1.70E-23), IRF5 (p = 2.30E-08), IRF7 (p = 1.90E-29), IRF8 (p = 0.029), IRF9 (p = 4.80E-05) expression and pathological grade." (PMID 33902005, 2021). "Collectively, these results indicate that IRF family members, including IRF1, IRF2, IRF5, IRF8 and IRF9, may serve as prognostic biomarkers and indicators of immune status in glioma patients." (PMID 33902005, 2021). "Overall survival curves indicated that glioma patients with lower IRF1 (p = 4.42E-33), IRF2 (p = 2.22E-16), IRF3 (p = 1.43E-15), IRF4 (p = 0.004), IRF5 p = 5.84E-12), IRF7 (p = 6.85E-28), IRF8 (p = 0.001), and IRF9 (p = 0.000) transcript levels had significantly longer overall survival times." (PMID 33902005, 2021).
Hodgkins lymphoma (9 papers, 2016 to 2025). A heterogeneous group of malignant lymphoid neoplasms of B-cell origin characterized histologically by the presence of Hodgkin and Reed-Sternberg (HRS) cells in the vast majority of cases. "In Hodgkin lymphoma, upregulation of the oncogenic factor interferon regulatory factor 5 (IRF5) was driven by the transcriptional activation of a normally dormant HERV LOR1a-LTR upstream of IRF5." (PMID 35928153, 2022). "In fact, a later study identified an additional derepressed LTR to result in the activation of interferon regulatory factor 5 (IRF5), a transcription factor previously shown to be necessary for the survival of Hodgkin Lymphoma cells." (PMID 32993145, 2020). "In addition, the TE-derived transcript annotation allowed us to reconfirm a previously reported onco-expansion phenomenon in Hodgkin’s lymphoma: the LOR1a-IRF5 fusion transcript." (PMID 40770674, 2025). "Distinct from the multitude of solid cancers and hematologic malignancies that have been shown to have lost IRF5 expression, a tumor-promoting role for IRF5 was identified in classical Hodgkin Lymphoma (HL) where IRF5 expression was found to be elevated and over-activated in HL B cells." (PMID 30515152, 2018). "In Hodgkin Lymphoma cell lines, the pro-inflammatory factor IRF5 is upregulated, following the activation of an LTR-IRF5 chimeric transcript." (PMID 35326499, 2022). "Likewise, derepresssion of an ERV, LOR1a LTR upstream of IRF5 transcription factor interferon regulatory factor 5 (IRF5), forms LTR-IRF5 chimeric transcripts, which derives IRF5 expression as a feature of malignancy in hodgkin lymphoma." (PMID 32509768, 2020).
myocardial infarction (9 papers, 2016 to 2025). Gross necrosis of the myocardium, as a result of interruption of the blood supply to the area, as in coronary thrombosis. "For example, nanoparticle-delivered siRNA targeting Irf5 in macrophages promotes inflammation resolution, improves infarct healing, and attenuates post-myocardial infarction remodeling." (PMID 40315012, 2025). "In a mouse model of myocardial infarction, knockdown of IRF5 alters macrophage polarization, accelerates inflammatory regression, increases fibrosis in the infarct zone, accelerates the rate of tissue repair and attenuates heart failure." (PMID 39087342, 2024). "A similar study using nanoparticle-mediated IRF5 siRNA delivery in vivo into macrophages residing in myocardial infarcts (MI) and in surgically induced skin wounds in mice showed resolution of inflammation and infarct healing." (PMID 30515152, 2018). "By upregulating miR-125a-5p and inhibiting the TRAF6/IRF5 signaling pathway, macrophage polarization toward the M2 phenotype is promoted, reducing the inflammatory response after myocardial infarction, improving cardiac function and structure, and alleviating AMI." (PMID 41583440, 2025). "IRF5 regulates a series of pro‐inflammatory genes by controlling the expression of downstream pro‐inflammatory cytokines involved in MyD88‐dependent Toll‐like receptor signalling, which exacerbates the inflammatory response after myocardial infarction." (PMID 39087342, 2024). "Similarly, IRF5 silencing via siRNA in ApoE-/- mice results in decreased M1 macrophages and accelerated wound healing after myocardial infarction, whereas transgenic absence of IRF5 gene (i.e., ApoE-/- IRF5-/- double knock-out) results in decreased necrotic core formation." (PMID 33805303, 2021).
ovarian carcinoma (9 papers, 2019 to 2024). A malignant neoplasm originating from the surface ovarian epithelium. "We next conducted a detailed phenotypic and functional analysis of macrophage/monocyte populations in the peritoneum of mice with established ovarian cancer following treatment with IRF5/IKKβ nanoparticles or PBS over a 3-week period (two weekly injections)." (PMID 31481662, 2019). "Coexpression of IRF5 and IKKβ (a kinase that phosphorylates and activates IRF5) mediates TAM polarization toward the M1 phenotype, suppressing tumor development in model systems of advanced-stage ovarian cancer, metastatic melanoma, and glioblastoma." (PMID 39516356, 2024). "Indeed, BATF3, IRF5 and ZBTB38 also contributed in evaluation of the response to chemotherapy of breast and ovarian cancer patients." (PMID 35410350, 2022). "Furthermore, co-expression of IRF5 and IKKβ (a kinase that phosphorylates and activates IRF5) mediates TAM polarization towards M1 phenotype, supressing tumor development in model systems of advanced-stage ovarian cancer, metastatic melanoma, and glioblastoma." (PMID 32486098, 2020). "To measure how much the anti-tumor responses we achieved with IRF5/IKKβ NP macrophage reprogramming were mediated by host T cells, we next used monoclonal antibodies to deplete CD8+ T cells in mice with established ID8 ovarian cancer." (PMID 31481662, 2019).
psoriasis (9 papers, 2007 to 2025). An autoimmune condition characterized by red, well-delineated plaques with silvery scales that are usually on the extensor surfaces and scalp. "The interferon regulatory factor gene IRF5 is predicted by TWAS to be upregulated across tissues in the presence of psoriasis risk variants at the newly reported 7q32.1 locus." (PMID 40021644, 2025). "A long non-coding RNA RP11-977G19.11 and a well-known psoriasis risk gene, interferon regulatory factor 5 (IRF5), were identified in every tissue except for spleen and EBV-transformed lymphocytes, respectively." (PMID 37511476, 2023). "On the contrary, in the present study, IRF5 deficiency unexpectedly exacerbated psoriasis-like skin inflammation." (PMID 32456211, 2020). "This study demonstrated whether and how the congenital deficiency of IRF5 was involved in the immunological development of psoriasis using an imiquimod-induced psoriasis-like skin inflammation." (PMID 32456211, 2020). "Thus, IRF5 deficiency exacerbated imiquimod-induced psoriasis-like skin inflammation." (PMID 32456211, 2020). "In this study, we investigated the role of IRF5 in psoriasis using imiquimod-induced psoriasis-like dermatitis." (PMID 32456211, 2020). "We next examined the messenger RNA (mRNA) expression levels of psoriasis-related cytokines in the skin lesions in WT and IRF5 KO mice." (PMID 32456211, 2020). "In psoriasis patients, there is an interaction between the IRF5 gene variants and major histocompatibility complex (MHC) class I gene locus, suggesting that IRF5 should be related to the development of psoriasis." (PMID 32456211, 2020). "Thus, during the clinical course of imiquimod-induced psoriasis-like skin inflammation, the amplification of Th17 responses caused by the up-regulation of IL-23 expression, the impairment in type I interferon and inflammatory cytokines and the decrease in IL-10 expression occurred in IRF5 KO mice." (PMID 32456211, 2020). "We therefore studied the role of IRF5 in the development of psoriasis using a psoriasis-like inflammation model induced by imiquimod, a ligand for Toll-like receptor (TLR)-7 in IRF5-deficient mice." (PMID 32456211, 2020). "In this study, we tested three genes, namely, IL23R, IRF5 and CD40, which have been associated with other immune-mediated diseases, including Crohn's disease (CD), psoriasis, SLE and GD, for an association with type 1 diabetes." (PMID 18045485, 2007). "To examine the role of IRF5 during psoriasis-like skin inflammation, we first applied imiquimod cream on mouse back skin and ear, and investigated the clinical and histopathological features of wild-type (WT) and IRF5 knockout (IRF5 KO) mice." (PMID 32456211, 2020). "Congenital IRF5 deficiency induces the upregulation of IRF4 in DCs followed by an augmented IL-23 production from DCs, resulting in the amplification of Th17 responses and the exacerbation of imiquimod-induced psoriasis-like skin inflammation." (PMID 32456211, 2020). "Taken together, our results suggest that IRF5 deficiency induces the upregulation of IRF4 in DCs followed by augmented IL-23 production, resulting in the amplification of Th17 responses and the exacerbation of imiquimod-induced psoriasis-like skin inflammation." (PMID 32456211, 2020). "The regulation of IRF4 or IRF5 expression may be a novel therapeutic approach to psoriasis." (PMID 32456211, 2020). "Finally, we did not obtain any evidence of an association between type 1 diabetes and IL23R, IRF5 or CD40, all of which have previously been associated with other immune-mediated diseases including, most recently, IL23R in Crohn's disease and in psoriasis." (PMID 18045485, 2007). "In conclusion, our results demonstrate that both IRF5 and IRF4 may have an important role in the pathophysiology of psoriasis." (PMID 32456211, 2020).